BDNF (brain derived neurotrophic factor)
Diseases named in the same sentence as BDNF in open-access papers (continued):
Sharing a sentence is not in itself a finding about the gene and the disease.
cancer (continued). "We previously reported baseline data from AYAC and non-cancer controls enrolled in the Adolescent and Young Adult Cancer Patients: Cognitive Toxicity on Survivorship (ACTS) study, as well as associations between BDNF with cognition from six months post-baseline." (PMID 40597835, 2025). "Circulating BDNF can be detected in endothelial cells, cardiomyocytes, smooth muscle cells, and blood cells such as leukocytes and platelets, which indicates its potential role in various disease processes, including neurodegenerative disorders, cardiovascular diseases, and cancer." (PMID 40002745, 2025). "Therefore, BDNF/TrkB and its downstream targets are potential targets for cancer therapy." (PMID 39648800, 2024). "Thus, the BDNF inhibits cell apoptosis and facilitates cell proliferation in various human cancers." (PMID 38775506, 2024). "In conclusion, this study provides evidence of a possible correlation between the development of cancer and SCZ-like behaviors and suggests that TNFR2 and its effects on BDNF expression could be important in the mediating the relationship between cancer and SCZ development." (PMID 38592583, 2024). "However, the relationship between the BDNF rs6265 polymorphism and cancer-related fatigue in female cancer survivors has not been fully investigated." (PMID 37462904, 2024). "For example, miRNA-210 targeting brain-derived neurotrophic factor (BDNF), microglia modulating miRNA-21, and miRNA-27a and -132 modulating Tau would help to explain what pathway triggers a neuron to turn into an undifferentiated and immortal cancer cell or broken dying cell." (PMID 36834933, 2023). "However, the impact of physical activity on BDNF levels in patients with cancer (including HGG), remains unclear at present." (PMID 37959303, 2023). "Furthermore, regulatory interaction between BDNF and miRNAs could modulate the proliferation of cancer cells." (PMID 35916975, 2022). "It was worth noting that BDNF and its similar genes were notably associated with EGFR tyrosine kinase inhibitor resistance, which might provide evidence for their potential role in cancer-targeted treatment." (PMID 34777634, 2021). "Similarly, the role of BDNF in various cancer processes have been reported as well." (PMID 34685742, 2021). "BDNF may modulate cancer cells’ sensitivity to standard drugs." (PMID 34395067, 2021). "Thus, we suspected that combining BDNF blockade and ICIs might be a feasible approach to eliminate cancer cells." (PMID 34777634, 2021). "Intriguingly, our analyses revealed that the degree of BDNF expression was correlated with high chemotherapeutics sensitivity and highly expressed immune checkpoints, making it a valuable biomarker in predicting the therapeutic benefits for chemotherapy and immunotherapy in cancer patients." (PMID 34777634, 2021). "In addition, the release of BDNF from cancer cells may also be involved in that cross talk between stroma and cancer, facilitating a microenvironment favorable for cancer metastasis." (PMID 33294440, 2020). "Taking into account that hyperoxic exposure results in ROS formation, increased oxidative stress and increased BDNF expression, BDNF may mediate hyperoxia effects offering cancer cell a survival advantage by several mechanisms like increased angiogenesis and EMT." (PMID 32183322, 2020). "In addition, other studies have suggested that BDNF is produced by several types of cancer." (PMID 31339548, 2019). "Moreover, MTX also influences BDNF, a factor that is expressed specifically in embryonic neural progenitor cells, regulates extensively adult neurogenesis and neuroplasticity, and plays a promoting role in cancer." (PMID 29177029, 2017). "Moreover, neurotrophin signaling pathways may function as endogenous systems that protect neurons after biochemical insults, transient ischemia, or physical injury; in other studies, however, BDNF showed anti-cancer potential." (PMID 27145455, 2016).
cancer (continued). "Therefore, MMP-1 might be the BDNF-responsive mediator, which causes the degradation of the ECM, resulting in subsequent cancer migration and invasion activity." (PMID 23892595, 2013). "Our findings revealed a significant increase in BDNF and Ghrelin levels following the yoga intervention, supporting the hypothesis that yoga may be an effective adjunct therapy to improve cognitive function, metabolic health, and inflammatory responses in cancer survivors." (PMID 41128015, 2025). "Heterogeneity at post-intervention was moderate-to-high for CRP, IL-6, IL-6-CNS, IL-6-cancer, TNF-α, IL-10, IFN-γ, BDNF, and cortisol." (PMID 40281902, 2025). "The BDNF and its receptor TrkB have been found to be specifically expressed in HCC cell lines and tumor tissues and to induce neovascularization and cancer cell survival/invasion." (PMID 40806192, 2025). "Consistently, our pathway analysis revealed that target genes of RUNX1 participate in key pathways, which have been previously reported in this type of cancer, such as Pathways in cancer, WNT signaling pathways and the BDNF signaling pathway." (PMID 41020879, 2025). "Recent studies have shown that cancer cells express neurotrophic markers such as NGF, BDNF, and GDNF and release axon guidance molecules such as Ephrin B1 to promote axonogenesis, neurogenesis, and neuronal reprogramming." (PMID 38920662, 2024). "Brain-derived neurotrophic factor (BDNF), a part of the neurotrophic factors, possesses the capacity to invigorate cancer cell growth, survival, proliferation, apoptosis evasion, and migration." (PMID 38243240, 2024). "The expression of another neurotrophic factor, brain-derived neurotrophic factor (BDNF) is downregulated in PD and other neurodegenerative disorders and upregulated in various types of cancers." (PMID 38612708, 2024). "BDNF/TRKB-mediated activation of these pathways contributes to increased cell growth, resistance to apoptosis, and the ability of cancer cells to invade surrounding tissues." (PMID 37445902, 2023). "BDNF and EGF act on downstream receptors [tropomyosin receptor kinase b (TrkB) and EGFR] on the surface of cancer cells and activate pathways ensuring cancer cell invasiveness." (PMID 37056723, 2023). "Trks bind to nerve growth factors (NGFs), such as brain-derived neurotrophic factor (BDNF) and NGF, which are secreted by nerves and cancer cells, and promote cancer cell survival, migration, and proliferation." (PMID 37566075, 2023). "We identified high expression of BDNF and TRKB in cancer cells as well as in stromal cells such as fibroblasts and vascular endothelial cells." (PMID 36266462, 2022). "APOE, BDNF, and COMT candidate genes have demonstrated influence on neurocognition in oncology populations, though limited data exists specific to pediatric cancer and CNS tumor populations." (PMID 35814456, 2022). "Novel DNA methylation biomarkers for the prognosis during the early stages of cancer, such as INHBB, SMOC2, BDNF, and TBRG4, are being tested for clinical use to improve detection methods and guide the treatment and diagnoses of cancer patients." (PMID 34827720, 2021). "In PNI, cancer cells spread along and within the neural sheath of nerves, and their migration is regulated by the action of growth factors (e.g., NGF, BDNF) that are involved in axon guidance." (PMID 34503281, 2021). "These molecules, such as BDNF, must be upregulated in response to transient increased ROS and, at the same time, be able to induce cell survival, cell proliferation and EMT of cancer cells." (PMID 34572400, 2021). "Brain-derived neurotrophic factor (BDNF), a growth factor with relevance in several cancer types, was also found strongly to be induced in the absence of NCOR1." (PMID 34503224, 2021). "Brain-derived neurotrophic factor (BDNF) reduces hypothalamic inflammation and increases sympathetic activation, thereby inhibiting cancer growth." (PMID 34899611, 2021).
cancer (continued). "Several inflammatory cytokines, such as CD31, BDNF, TFF3, Serpin E-1, VCAM-1, Vitamin D BP, and PDGF-AA, were significantly upregulated in cancer survivors while MMP9 and Osteopontin both had significant positive correlations with barriers to care." (PMID 32587352, 2020). "Human malignant glioma samples and cancer stem cells (CSCs) isolated from human gliomas express NGF, BDNF, NT3, TrkB, and TrkC." (PMID 32906676, 2020). "The BDNF/TRKB axis has been shown to be activated in several human malignancies with important effect on cancer cells behavior." (PMID 33294440, 2020). "The usual suspects for epilepsy, namely brain derived neurotrophic factor (BDNF) detected from the neurotrophin and solute carrier family 2 member 1 (SLC2A1/GLUT1) from the cancer pathway are highlighted via this approach." (PMID 30735541, 2019). "Cancer accounts for only 3.3% of total diseases related to selected myokines (apelin, BDNF, IL-15, irisin, SPARC), but additional myokines have been shown to be more clearly involved in cancer cachexia." (PMID 30984014, 2019). "In TNBC cells, brain-derived neurotrophic factor (BDNF) binds and activates TRKB receptor to regulate a network consisting of metalloproteases and calmodulin and thus modulate cancer–endothelial cells interaction." (PMID 29520340, 2018). "The oncostatin M, BDNF and TGF-β pathways have been demonstrated to co-operate to drive EMT and cancer stem cell expression signatures in other cancers." (PMID 29339786, 2018). "PNI is influenced by the interaction between the nerve microenvironment and neurotrophic molecules expressed by cancer cells such as nerve growth factor (NGF), BDNF, glial cell line-derived neurotrophic factor (GDNF) and their receptors." (PMID 29334991, 2018). "It is also important to note that BDNF and VEGF/VEGFR play different roles in the multi-step process that makes up cancer metastasis." (PMID 28604807, 2017). "Our previous studies have shown that brain-derived neurotrophic factor (BDNF) participates in the process of metastasis and in the migration of cancer cells." (PMID 28604807, 2017). "The brain-derived neurotrophic factor (BDNF) activates its receptor, tropomyosin receptor kinase B (TrkB; also called NTRK2) that has been shown to promote the malignant progression of several cancers." (PMID 27458153, 2016). "Tropomyosin receptor kinase B (TrkB), a receptor of brain-derived neurotrophic factor (BDNF), induces cancer metastasis by suppression of anoikis." (PMID 23599747, 2013). "Among these mechanisms, the Tyrosine Receptor Kinase B and Brain Derived neurotropic Factor (TrkB/BDNF) system has been reported to be responsible for chemoresistance, through Akt/PI-3K and MAPK signaling pathways, in selected models of cancer." (PMID 22276165, 2012). "Notably, these findings provide novel insight on relationships between inflammation, BDNF, and CRCI that are unique to the cancer population by limiting age-related confounders." (PMID 40597835, 2025). "The most investigated genes were those implicated in neuroendocrine stress responses; dopamine, norepinephrine, and serotonin signalling; apoptosis; insulin secretion; neuroplasticity; reproduction; foetal growth; and cancer (e.g. MAOA, BRSK2, ADCYAP1, BDNF, DRD2, IGF2, H19)." (PMID 41070359, 2025). "These compounds are used to target different nuclear receptors of cancer which includes peroxisome proliferator-activated receptor gamma (PPARγ), toll-like receptor 4 (TLR4), brain-derived neurotrophic factor (BDNF), and peroxisome proliferator-activated receptor alpha (PPARα)." (PMID 41459064, 2025). "BDNF-mediated downstream signaling pathways – including the MAPK/ERK cascade, PLCγ/DAG/PKC pathway, and PLCγ/IP3 cascade – play a key role in the persistence of in inflammatory pain, neuropathic pain, and cancer pain." (PMID 40811566, 2025).
cancer (continued). "By comparing the effects of growth factor treatment on the control and SORL1 knockdown cell lines, we identified that SORL1 was involved in the cancer cell growth stimulated by CXCL12, BDNF, FGF1, and EGF1 in OVCAR8 cells and by BDNF, FGF1, and EGF1 in KRCH31 cells." (PMID 39858026, 2025). "Consistently, BDNF is also overexpressed in OSCC and leads to cancer pain via binding to TrkB." (PMID 38334648, 2024). "Furthermore, the study investigated the role of BDNF and its receptor TrkB in mediating the development of both SCZ and cancer." (PMID 38592583, 2024). "Within tumors, nerve cells release several neurotrophic factors that can modulate the proliferation and phenotype of cancer cells, including Nerve Growth Factor (NGF), Neurotrophins (NT), Brain-Derived Neurotrophic Factor (BDNF) or Glial Cell Line-Derived Neurotrophic Factor (GDNF)." (PMID 38375479, 2024). "A total of 394 female cancer survivors were included in this analysis, but one study participant was excluded due to a lack of BDNF genotypic data." (PMID 37462904, 2024). "BDNF activates tropomyosin-related receptor kinase B (TrkB), initiating critical signaling pathways such as RAS/MAPK, PI3K/Akt, and JAK2/STAT3, which influence cancer progression and affect cellular processes including proliferation and migration." (PMID 39401197, 2024). "In addition to NGF, tumors also secrete other neurotrophic substances such as brain derived neurotrophic factor (BDNF), which is closely related to cancer pain." (PMID 37007073, 2023). "Interestingly, the growth factors (e.g., TGF-beta, PDGF, and EGF) are prominent inducers of EMT, whereas the BDNF/TrkB pathway proved effective modulator of EMT in different cells and cancer progression." (PMID 37645595, 2023). "Several lines of evidence support the hypothesis that cancer cell support neurogenesis by secreting different neurotrophic factors such as nerve growth factor (NGF), brain-derived neurotrophic factor (BDNF), and neurotrophin 3 (NT3)." (PMID 36289793, 2022). "We observed that BDNF and TRKB were highly expressed in both cancer cells and mesenchymal cells." (PMID 36266462, 2022). "Given the poor prognosis of many human cancers in which tropomyosin receptor kinase B (TRKB) is highly expressed, we investigated the involvement of brain-derived neurotrophic factor (BDNF)/TRKB pathway in PGC cells using clinical specimens and observed upregulation of TRKB and BDNF." (PMID 36266462, 2022). "Although CM from co-cultures of PGC cells with CAFs did not increase BDNF expression in CAFs, our data do not exclude the possibility that BDNF, which is secreted by CAFs, regulates cancer cell functions." (PMID 36266462, 2022). "Previous studies have presented neurotransmitters and neurotrophins (e.g., substance P, nerve-growth factor (NGF) and brain-derived neurotrophic factor (BDNF)), chemokines (e.g., CX3CL1 and CCL2), extracellular vesicles, and Schwann cells as key players in cancer–nerve crosstalk." (PMID 35565690, 2022). "While no distinct link between lactate and cancer–nerve crosstalk has been confirmed, BDNF is a known contributor of both PNI and TI; therefore, continued examinations of the role of lactate in this relationship are warranted." (PMID 35565690, 2022). "Although the sample size of patients with PE and cancer was reduced in our study group, the BDNF levels were not significantly influenced in these patients." (PMID 36078878, 2022). "We found no substantial differences in the pre- or postoperative serum BDNF concentrations between groups with and without lymphatic invasion, in either type of cancer." (PMID 34395067, 2021). "Other mitogens, including the BDNF and VEGF, could also be important contributors for the growth of brain-metastatic cancer cells." (PMID 34373757, 2021). "Since the cancer-promoting effects of BDNF in RB are confirmed by previous studies, we concluded that XIST exerted its cancer-promoting effect partly by up-regulating the expression of BDNF." (PMID 33942699, 2021).
cancer (continued). "There is increasing evidence of potential genetic (APOE, COMT, BDNF), plasma (e.g., inflammatory molecules, circulating microRNAs, exosomes, short-chain fatty acids and others), cerebrospinal fluid and neuroimaging biomarkers of CRCI in cancer patients." (PMID 34970595, 2021). "Results showed significantly higher mRNA levels in cancer tissues compared with normal pancreas for BDNF but not for TrkB receptor." (PMID 34395067, 2021). "Additionally, this drug has been demonstrated to regulate important cellular dynamics particularly during cancer progression (i.e., modulation of PI3K/Akt/mTOR activity) while promoting normal brain health through induction of BDNF." (PMID 33013390, 2020). "Despite the importance of BDNF on brain functions and increasing interest in Val66Met on psychiatric/cognitive symptoms, studies on the effects of Val66Met on cancer-related fatigue are non-existent." (PMID 32848137, 2020). "We are performing BDNF, NGF, FAK, ADRb2 and NLRP3 assessments by qPCR in extracellular vesicles from plasma and platelets by qPCR in advanced cancer patients and preliminary results show that responders correlate with diminishing levels, mainly, of NGF and BDNF (unpublished data)." (PMID 32516941, 2020). "Importantly, analysis of BDNF staining in 4T1BR5 experimental BM showed increased BDNF expression in cancer cells in E2-treated mice, compared with OVX-treated mice, suggesting that E2 promotes BDNF upregulation in BM." (PMID 30796353, 2019). "Moreover, BDNF cross-activated TrkB and EGFR in cancer cells expressing both receptors, suggesting a novel cooperative interaction between these signaling pathways in TNBC." (PMID 30796353, 2019). "In addition, higher S100A4 expression was observed in various cancer types compared to MYLK, BDNF, and PCOLCE2." (PMID 31581665, 2019). "Cancer cells were exposed to medium from either BDNF-depleted CAFs (BDNF-shRNA) or non-targeted CAFs (NT-shRNA)." (PMID 28966935, 2017). "Human cancer cell lines Caco-2, HRT18 and RKO were examined for the presence of BDNF using RT-PCR." (PMID 24255678, 2013). "Mechanistically, the activation of TrkB by BDNF has shown to activate various intracellular signaling pathways including Akt, Src, or MAPK resulting in cell proliferation, and apoptosis resistance in models of human cancer." (PMID 22276165, 2012). "Since AKT and Rac1 require each other for their activation, our findings suggest that loss of miR-204 expression in human tumors may induce the positive feedback loop between BDNF/AKT1/mTOR and Rac1 during cancer cell migration and invasion." (PMID 23285024, 2012). "Thus, early detection of actin could serve as a biomarker to predict the emergence of tobacco related disorders (cancers, heart diseases), while MBP abnormalities and low BDNF levels might serve as early biomarkers for FASD." (PMID 40061215, 2025). "In PDAC, neurogenesis is a novel studied biological phenomenon since cancer cells may induce nerve growth and innervation through multiple mechanisms, including secretion of neurotrophic factors such as NGF, BDNF, and the glial cell-derived neurotrophic factor (GDNF)." (PMID 40806192, 2025). "Additionally, several studies showed that BDNF levels were significantly increased, rather than decreased, in patients with various types of cancer, but without PE." (PMID 36078878, 2022). "Assigned study not assumed measurement of TrkB and BDNF in cancer tissues what might additionally limit our conclusions, especially concerning BDNF/TrkB as a potential target for novel anticancer therapies." (PMID 34395067, 2021). "In noncancer populations, BDNF mediates the effects of physical activity on neurocognitive outcomes and is positively related to objective and self-reported cognition in cancer patients." (PMID 31605514, 2019).